PIK3CD (phosphatidylinositol-4,5-bisphosphate 3-kinase catalytic subunit delta)
Diseases named in the same sentence as PIK3CD in open-access papers (continued):
Sharing a sentence is not in itself a finding about the gene and the disease.
peripheral T-cell lymphoma (1 paper, 2024). "In addition, phosphatidylinositol-4,5-bisphosphate 3-kinase catalytic subunit delta (PIK3CD), mitogen-activated protein kinase kinase kinase 7 (MAP3K7) and mitogen-activated protein kinase kinase 6 (MAP2K6) are downregulated in peripheral T-cell lymphoma during chemotherapy resistance." (PMID 38468267, 2024).
primary sclerosing cholangitis (1 paper, 2024). "Previously only two adult patients with PIK3CD mutations had primary sclerosing cholangitis." (PMID 38287413, 2024).
proliferative diabetic retinopathy (1 paper, 2024). Advanced retinopathy due to diabetes mellitus characterized by the formation of new vessels in the retina. "Furthermore, decreased DNA methylation in the CpG site annotated to PIK3CD is identified in individuals with proliferative diabetic retinopathy." (PMID 38904047, 2024).
Respiratory tract infection (1 paper, 2023). An infection of the upper or lower respiratory tract. "In our case, the child had a history of respiratory tract infection, recurrent diarrhea, and high IgM immunophenotype, and genetic testing revealed a heterozygous causative mutation carrying the PIK3CD gene, which confirmed the diagnosis of APDS." (PMID 36749229, 2023).
Sturge-Weber syndrome (1 paper, 2024). Sturge-Weber syndrome (SWS) is a rare congenital neurocutaneous disorder characterized by facial capillary malformations and/or cerebral and ocular ipsilateral vascular malformations that result in variable degrees of ocular and neurological anomalies. "Case reports have been published for GNB2, CBL and PIK3CD, describing patients with Sturge-Weber syndrome (GNB2) or lymphatic anomalies (CBL and PIK3CD)." (PMID 38778413, 2024).
sudden sensorineural hearing loss (1 paper, 2022). Sensorineural hearing loss which develops suddenly over a period of hours or a few days. "Pik3cd encodes a phosphoinositide 3-kinase that is involved in the immune response, has been previously associated with idiopathic sudden sensorineural hearing loss, and is targeted by the drug idelalisib, approved to treat certain blood cancers." (PMID 35454087, 2022).
testicular tumors (1 paper, 2021). "KRAS mutations were present in 10% of testicular tumors, while fewer than 5% of samples contained mutations in NRAS, PIK3CD, and PIK3CA genes." (PMID 34819066, 2021).
Thrombocytopenia (1 paper, 2023). A reduction in the number of circulating thrombocytes. "If whole exome sequencing suggests a variant in PIK3CD gene, sirolimus may relieve hepatosplenomegaly and resistant thrombocytopenia." (PMID 37742016, 2023).
thyroid (1 paper, 2012). "The role of PIK3CD isoform in thyroid carcinogenesis remains to be determined, however it is worth stressing that PIK3CD contributes in other neoplastic processes." (PMID 23259526, 2012).
thyroid cancer (1 paper, 2019). "Some genes that we found to be epigenetically upregulated in OSCC-GB patients, such as PIK3CD and IFITM1, were earlier reported to be upregulated in thyroid cancer and HNSCC." (PMID 31796082, 2019).
Waldenstrom macroglobulinemia (1 paper, 2016). "In addition, dataset GDS2643 was analyzed to compare PIK3CD expression in B lymphocytes and PCs from healthy, Waldenstrom's Macroglobulinemia (WM), CLL and MM patients." (PMID 27229530, 2016).
cancer (112 papers, 2007 to 2025). A tumor composed of atypical neoplastic, often pleomorphic cells that invade other tissues. "In the majority of the 5 cancer types, PIK3CD expression was linked favorably with the expression of mesenchymal markers such as VIM (Vimentin), TWIST1, SNAI1 (SNAIL), SNAI2 (SLUG), and CDH2." (PMID 37861728, 2023). "Recently, PIK3CD has been reported to be associated with the homeostasis and function of B and T cells, and can induce cancer cell growth and invasion by activating AKT/GSK-3β/β-catenin signaling in CRC." (PMID 36246627, 2022). "In theory, SRPIN340 treatment could inhibit the synthesis of PIK3CD-S variant through blocking the exon 20 skipping in PIK3CD pre-mRNA, thereby enriching the PIK3CD-L (which is sensitive to Idelalisib treatment) in these cancer cells." (PMID 37670888, 2023). "PIK3CB and PIK3CD genes are rarely mutated in cancers but are often amplified or over-expressed." (PMID 28420128, 2017). "Importantly, our study provides greater granularity by being the first to demonstrate the relationship between expression of a race-enriched PIK3CD splice variant and cancer aggressiveness as well as resistance to SMIs targeting PI3Kδ." (PMID 28665395, 2017). "Likewise, Pik3cd, involved in the immune response and in cancer is implicated in the mTOR pathway with Ddit4 (also known as Redd1) and Tsc1/2." (PMID 23927422, 2013). "Upregulation of PIK3CD contributes to GC cell growth and metastasis both in vivo and in vitro, consistent with its roles in other cancer types reported previously." (PMID 38545256, 2024). "The IGF-1/IGF-1R signaling can activate the PI3K/AKT/mTOR pathway signaling pathway, which is closely related to AKT1 and PIK3CD and plays a critical role in glioma progression, promoting cancer cell proliferation and inducing drug resistance." (PMID 38665430, 2024). "PIK3CD appears to have important roles in the beginning and advancement of various forms of human cancer, according to mounting data." (PMID 37861728, 2023). "Numerous human cancers’ genesis and development have been shown to be significantly influenced by PIK3CD, among other things." (PMID 37861728, 2023). "The functions and fundamental mechanisms involving PIK3CD in cancer, however, are poorly understood." (PMID 37861728, 2023). "According to the survival analysis for the cancer types of interest, patients with high PIK3CD expression had a favourable outlook for survival (OS) in LUAD and BRCA and a poor outcome in PRAD and LUSC." (PMID 37861728, 2023). "Circular RNA ciRS-7 acted as a sponge of miR-7, upregulating several oncogenes (mTOR, EGFR, PIK3CD) to promote the progression of cancers in which high ciRS-7 expression correlated with worse prognosis and miR-7 acted as tumor suppressor." (PMID 35550610, 2022). "PIK3CD has recently been found to play a critical role in mediating the development of malignant tumors through activation of Akt signaling." (PMID 32555190, 2020). "Class I PI3K isoforms are relevant for cancer, i.e., p110α (encoded by the PIK3CA gene), p110β (PIK3CB gene), p110γ (PIK3CG gene), and p110δ (PIK3CD gene)." (PMID 30832253, 2019). "PI3Kγ (PIK3CD) is activated by only stimulated G-protein coupled receptors (GPCRs), and its role in cancer is controversial." (PMID 26267321, 2015). "Overexpression of PIK3CD and miR‐7 disrupts cancer cell migration through cell cycle arrest." (PMID 41409896, 2025). "In this investigation, we first used data from The Cancer Genome Atlas (TCGA) and Genotype-Tissue Expression (GTEx) to do a pan-cancer analysis of PIK3CD expression.PIK3CD was significantly downregulated in 10 tumor types, including BRCA, COAD, LIHC, LUAD and LUSC." (PMID 37861728, 2023). "In our study, we first examined the expression and survival of PIK3CD in diverse human cancers." (PMID 37861728, 2023).
cancer (continued). "Meanwhile, PIK3CD is mapped to three (duvelisib, idelalisib, and copanlisib) types of cancer drugs." (PMID 35052792, 2022). "Surprisingly, there were no de novo genetic variants found in PIK3CD given that variants of PIK3CD have been identified previously in a range of cell lines of other cancer types." (PMID 33549048, 2021). "There are three class IA p110 isoforms (α, β, δ) expressed by the genes phosphatidylinositol-4,5-bisphosphate 3-kinase catalytic subunit alpha (PIK3CA), PIK3CB and PIK3CD, respectively, of which PIK3CA is the most frequently mutated in multiple cancer types, including EOC." (PMID 35582310, 2021). "PIK3CD, whose ectopic expression could affect the biological phenotypes of multiple cancers, was reported to regulate the PI3K signaling pathway." (PMID 31894857, 2020). "Three different genes, PIK3CA, PIK3CB, and PIK3CD, encode three specific p110 isoforms, p110α, β, and δ, respectively, and activating missense mutations of PIK3CA have been found as oncogenic in a variety of cancers." (PMID 30682771, 2019). "Class IA PI3Ks (PIK3CA, PIK3CB, and PIK3CD) are the most important isoforms in cancer." (PMID 29642462, 2018). "Activating mutations in the PIK3CA gene encoding the p110α catalytic subunit of class IA PI3K are frequently mutated in several cancer types, and mutations in the PIK3CD gene encoding the p110δ catalytic subunit have been identified in primary immunodeficiency patients." (PMID 29616047, 2018). "Interference with PIK3CD expression at the promoter level may offer a novel therapeutic target in cases of aberrant p110δ overexpression, as observed in some cancers." (PMID 19357769, 2009). "In this regard, PIK3CD may be a candidate factor involved in inflammation to cancer transformation." (PMID 38545256, 2024). "In addition, PTK2 protein tyrosine kinase 2 (PTK2), phosphatidylinositol 3-kinase regulatory subunit gamma (PIK3R3), and phosphatidylinositol-4,5-bisphosphate 3-kinase catalytic subunit delta (PIK3CD) are shown to be related to pathways in cancer (KEGG ID: map 05200)." (PMID 30255812, 2018). "Topological analysis of the PPI network, using the STRING database and Cytoscape 3.10.2, identified seven core targets crucial in cancer pathways: CYP3A4, PIK3R1, PIK3CD, ESR1, AKR1C3, EGFR, and CYP19A1." (PMID 39204124, 2024). "The differential expression of PIK3R1, AKR1C3, EGFR, ESR1, PIK3CD, CYP3A4, and CYP19A1 across various cancer types and stages illuminates their potential as biomarkers for cancer progression and prognosis." (PMID 39204124, 2024). "At the same time, we also found positively selected differentially edited sites in a series of cancer immune genes, including EGF, IGF1R, and PIK3CD." (PMID 36895481, 2023). "PIK3CD contributes in the PI3K signalling pathway, which plays an important role in the development of various cancers." (PMID 33126409, 2020). "miR-7-5p is more of a tumor suppressor that represses oncogenic proteins such as EGFR, IGF1R, IRS-1, IRS-2, RAF1, PIK3CD, mTOR, and PI3K, in various cancers including PDAC, liver, breast, non-small cell lung carcinoma (NSCLC), colorectal (CRC) and ovarian." (PMID 31510100, 2019). "To date, it has been well established that miR-7 directly targets many oncogenic factors and is involved into multiple cancer-related signalling pathways, including EGFR, IRS-1/2, Raf1, Pak1, Ack1, PA28-gamma, IGF1R, PIK3CD and mTOR32–38." (PMID 28710406, 2017). "PIK3CD, instead, belongs to the same class I of PIK3CA/B/G and has been found amplified or overexpressed in cancer." (PMID 26860319, 2016). "PIK3CD, PIK3R2 and PIK3CA are all members of the Class I phosphoinositide 3-kinase (PI3K) enzymes, which have been shown to be involved in several types of cancer and involved in the Akt/mTOR pathway." (PMID 26473850, 2015).
cancer (continued). "Although all class IA PI3K p110 isoforms may have important functions in human cancers via AKT activation, in our study we found that only PIK3CD (p110δ) expression is induced by pro‐inflammatory responses and immune infiltration cells." (PMID 38545256, 2024). "Nevertheless, proteins p100β, p100δ, and p100γ are also capable of inducing oncogenic transformation in their wild-type form, in line with the fact that PIK3CB, PIK3CD, and PIK3CG are generally amplified or overexpressed, but not mutated, in cancer." (PMID 32033478, 2020). "Importantly, target genes involved in epithelium development (RGMA, SHANK3, PAX6, PFN1, WNT4) and cancer (CBL, CYCS, FGF7, IGF1R, PTEN, PIK3CD, WNT4) address to a further role in the onset of epithelial abnormalities and oncogenesis." (PMID 23936163, 2013). "PIK3CD is mostly expressed in white blood cells and B cells and is crucial for the survival and maturation of B cell follicles, while PIK3CG expression is inversely correlated with colon cancer growth, despite the fact that PIK3CG levels are connected to cancer growth." (PMID 37176098, 2023). "Such active ingredients may influence neuroactive ligand-receptor interaction, calcium signaling pathways, signaling pathways in cancer, cAMP signaling pathways, and PI3K pathways by acting on multiple targets such as PTGS2, PIK3CA, PIK3CB, PIK3CD, F2, and AR to treat migraine." (PMID 36479181, 2022).
tumor (107 papers, 2007 to 2026). "Here we report that PIK3CD that encodes p110δ, a catalytic subunit of the class IA PI3Ks, is overexpressed and tumorigenic in GC and associated with tumor inflammatory microenvironment." (PMID 38545256, 2024). "We investigated the association between PIK3CD methylation and tumor-infiltrating lymphocyte abundance and discovered that it was strongly inversely linked with tumor-infiltrating lymphocyte abundance." (PMID 37861728, 2023). "Among these genes, four genes (TIMP1, MAPK13, MAPKAPK2 and MAPKAPK3) are known to regulate cell proliferation, and MMP2 and MMP9 control tumour-associated tissue remodelling; PIK3CD is involved in the immune response, and AKT2 regulates tumourigenesis." (PMID 32999349, 2020). "A group of genes have been identified as epigenetically affected in NB cell lines; the PIK3CD gene stands out as the most intriguing, since it also carries mutations in primary tumours, two patients with nonsynonymous mutations were identified." (PMID 17940511, 2007). "In addition to cascading with pro‐inflammatory signaling pathways, PIK3CD overexpression is also closely associated with the activation of tumor‐infiltrating immune cells such as CD8+ and CD4+ T lymphocytes, which is analyzed by TIMER algorithm." (PMID 38545256, 2024). "We discovered that PIK3CD expression had a positive relationship with the abundance of 28 different types of tumor-infiltrating lymphocytes and that PIK3CD methylation was strongly inversely linked with tumor-infiltrating lymphocyte abundance in the TISIDB database." (PMID 37861728, 2023). "The mutation in tumour 19R6 in the PIK3CD fits the two-hit hypothesis of tumour suppressor inactivation since it is also 1p deleted." (PMID 17940511, 2007). "Tumor development increased pik3cd and slc20a1 expression with respect to the healthy control group." (PMID 40284221, 2025). "By analyzing the tumor clone composition and the mutational landscape of the ibrutinib-resistant cells by WES we identified, according to SIFT, deleterious variants in PIK3CD (4:149658400 A/T) and VMN2R37 (7:9206799 G/C)." (PMID 39863584, 2025). "In CRC, PIK3CD is found to promote tumor cell proliferation and migration through activating AKT/GSK‐3β/β‐catenin axis." (PMID 38545256, 2024). "As concluded from the observation of removed tumors, we found that tumor weight of the PIK3CD knockdown group was significantly lower than that in the control group." (PMID 38545256, 2024). "Specifically, PI3Kδ is overexpressed in colorectal cancer (CRC), and ectopic expression of PIK3CD (gene encoding PI3Kδ) significantly activates the AKT signaling and promotes CRC cell growth, migration and invasion in vitro and tumor growth in vivo." (PMID 37670888, 2023). "Following correlation, expression, and survival analyses, miR-30b-5p was identified as the most likely upstream tumor suppressive miRNA of PIK3CD." (PMID 37861728, 2023). "We discovered that PIK3CD expression had a positive relationship with the abundance of 28 different types of tumor-infiltrating lymphocytes in the TISIDB database." (PMID 37861728, 2023). "Our findings reveal that PIK3CD expression is associated with prognosis, EMT, and tumor immune infiltration in BRCA patients." (PMID 37861728, 2023). "While PIK3C3 gene expression levels decreased with the progression of the disease passing from the primary tumours to metastatic forms, PIK3CD showed the opposite trend, with higher gene expression levels in metastatic BC forms than in primary tumours." (PMID 36012280, 2022). "The findings in vivo further indicated that CDR1as acted as an oncogene, up-regulating the proliferation index Ki-67, EGFR, CCNE1, and PIK3CD levels, thus inhibiting the anti-tumor effects of tumor suppressor miR-7." (PMID 34830377, 2021). "On the one hand, miR-7 targets and downregulates tumorigenic factors in tumour-associated signalling pathways such as PA28γ, EGFR, PAK1, ACK1 and PIK3CD, demonstrating the crucial role of miR-7 in tumour suppression." (PMID 33390839, 2021).